ENSG00000295333 (novel transcript)
Synonyms: ASMER-2; ASMER2
Gene: Long non-coding RNA gene on chromosome X (50,979,146 to 50,992,948, forward strand). Ensembl gene ENSG00000295333.
Diseases named in the same sentence as ENSG00000295333 in open-access papers:
ENSG00000295333 is named in the same sentence as 1 disease in open-access papers, as found by Europe PMC text mining. Sharing a sentence is not in itself a finding about the gene and the disease.
ENSG00000295333 shares sentences with these, for which no sentence is quoted: Obesity (1 paper).